SETP9 (SET pseudogene 9)
Gene: Transcribed processed pseudogene on chromosome 1 (160,670,148 to 160,670,979, forward strand). Ensembl gene ENSG00000235101.
Diseases named in the same sentence as SETP9 in open-access papers:
SETP9 is named in the same sentence as 2 diseases in open-access papers, as found by Europe PMC text mining. Sharing a sentence is not in itself a finding about the gene and the disease. The quoted sentences say what the papers report.
colorectal cancer (1 paper, 2014). A primary or metastatic malignant neoplasm that affects the colon or rectum. "Another exemplary diagnostic biomarker is the hypermethylation of SET pseudogene 9 (SETP9) in colorectal cancer, which can be sensitively and specifically detected in blood plasma and is able to differentiate between all the stages of the disease." (PMID 25473433, 2014).
SETP9 also shares sentences with these, for which no sentence is quoted: Sepsis (1 paper).